ATRX (ATRX chromatin remodeler)
Diseases named in the same sentence as ATRX in open-access papers (continued):
Sharing a sentence is not in itself a finding about the gene and the disease.
glioblastoma (continued). "ATRX mutations are observed in primary glioblastomas exhibiting IDH mutations." (PMID 30279357, 2018). "Moreover, it identifies potential treatment options for cancers associated with ATRX mutations, including glioblastoma and pancreatic neuroendocrine tumors." (PMID 23284920, 2012). "The observation that ATRX/DAXX mediates recruitment of H3.3 to telomeres is consistent with the finding that mutations in H3.3 may also be associated with ALT in pediatric glioblastomas, which suggests that ATRX, DAXX, and H3.3 act in the same pathway to repress ALT." (PMID 23185534, 2012). "Case 1 showed piloid morphology with ATRX mutation, loss of p16 (CDK2NA deletion), and a longer survival time compared with Case 2, which showed morphology and a molecular status similar to sporadic IDH-wildtype glioblastomas (nuclear ATRX and p16 retained)." (PMID 40277798, 2025). "CRISPR/Cas9 knockout ATRX glioblastoma cells demonstrated compromised H3K9 trimethylation, which led to decreased DNA repair by the tumor cells." (PMID 38279330, 2024). "The median values of peritumoral edema were higher in ATRX mutant cases compared to ATRX wild-type glioblastomas." (PMID 39684754, 2024). "ATRX mutations are common in secondary glioblastomas, particularly in IDH-mutant glioblastoma, but are rare in IDH wild-type patients, who generally have better survival outcomes." (PMID 39767571, 2024). "The chromatin remodeler ATRX and the histone chaperone DAXX are mutated in a variety of cancers, including glioblastoma multiforme, pediatric adrenocortical carcinoma, osteosarcoma, neuroblastoma, myelodysplastic syndrome, acute myeloid leukemia, and PNETs." (PMID 38279330, 2024). "Five of the nine tumors demonstrated somatic loss of ATRX protein expression that corresponded with those harboring inactivating ATRX mutations, which is known to be rare among IDH-wildtype glioblastomas in adults." (PMID 38079020, 2023). "Immunohistochemistry results indicated that GFAP, S-100, Olig-2, and ATRX were positive in more than 90% of glioblastomas." (PMID 37483487, 2023). "Instead, there were frequent inactivating mutations in ATRX known to cause alternative lengthening of telomeres (ALT) in five of the de novo RRD glioblastomas (5/9, 56%), which were rare in the conventional glioblastoma cohort (4/450, 1%)." (PMID 38079020, 2023). "Both TERT C228T and C250T promoter mutants were associated with IDH wildtype, preserved 1p/19q, histone wildtypes, and ATRX retention in glioblastoma cases." (PMID 37665980, 2023).
glioblastoma (continued). "Secondly, in WT hTERT and IDH glioblastoma, all ALT+ tumors have either ATRX loss or SMARCAL1 mutation." (PMID 34069193, 2021). "D06MG, a glioblastoma cell line with SMARCAL1 nonsense mutation and intact ATRX, was ALT+ as measured by APBs and C-circles." (PMID 34069193, 2021). "Currently, the biomarkers for glioblastoma are mostly molecular and include EGFRvIII, ATRX, PTEN, IDH1, MGMT, and others." (PMID 34462698, 2021). "The ATRX (alpha thalassemia/mental retardation X-linked) gene is mutated in approximately 5% of all cancers with the highest incidence in glioblastoma, neuroendocrine pancreatic cancer (53% with mutations in DAX/ATRX), non-small lung carcinoma and sarcoma." (PMID 31973211, 2020). "A study in ALT positive glioblastoma found that SMARCAL1 mutations, like those of ATRX and DAXX, correlate well with ALT status, with over half of ALT positive glioblastoma samples harboring SMARCAL1 mutations." (PMID 32039009, 2019). "For example, in pediatric glioblastoma multiforme (GBM), 31% of patients have mutations in either ATRX or DAXX36." (PMID 29479426, 2018). "Glioblastomas utilize distinct genetic mechanisms of telomere maintenance, either through TERT promoter mutation leading to telomerase activation or ATRX-mutation leading to ALT." (PMID 30279357, 2018). "Here, the authors present a genetic landscape of TERTpWT-IDHWT glioblastoma, identifying a telomerase-positive subgroup driven by TERT-structural rearrangements and an ALT-positive subgroup with mutations in ATRX or SMARCAL1." (PMID 29802247, 2018). "In glioblastomas of young adults and pediatric patients, some studies have identified a small percentage of patients who are IDH wild-type and have a loss of ATRX expression." (PMID 29034211, 2017). "Similar hypotheses can be also drawn for SMARCAL1 (which is often lost in ALT glioblastomas and is mutually exclusive with ATRX)." (PMID 40725011, 2025). "ATRX expression was observed as positive nuclear staining in tumor cells, consistent with its role in chromatin remodeling and indicating the presence of ATRX protein in the analyzed glioblastoma samples." (PMID 40282990, 2025).
glioblastoma (continued). "Furthermore, a heterogeneous category of IDH and ATRX wild-type tumors like glioblastoma multiforme (GBM) was defined as I-X." (PMID 38240992, 2024). "Concurrent mutations in IDH1 and ATRX have been described previously in glioblastoma and appear more prevalent in tumours without receptor tyrosine kinase (RTK) activation." (PMID 35324914, 2022). "ATRX mutations are extremely common in IDH-mutant glioblastomas but are typically not present in IDH-wildtype glioblastomas." (PMID 32678261, 2020). "In our cohort of 199 patients with glioblastoma, only 5 tumors demonstrated ATRX mutations without concomitant IDH mutations, and all IDH mutant tumors had associated ATRX mutations." (PMID 32678261, 2020). "Further molecular testing illustrated features more consistent with glioblastoma: multiple large chromosomal aberrations including loss of whole chromosome 1 and 2q; gain/amplification of MYCN, MET, and CDK4; loss of CDKN2A/B; and an ATRX mutation." (PMID 30738431, 2019). "Finally, we found that ATRX knockdown (sh590) in a glioblastoma-derived GSC (TS 543; IDH and ATRX wild type) enhanced G4 formation." (PMID 30808951, 2019). "Work in human glioblastomas has indicated that ATRX loss leads to a reduction in non-homologous end joining (NHEJ), and renders cells lacking ATRX sensitive to a number of DSB inducing agents and ionizing radiation (IR)." (PMID 32039009, 2019). "Another study showed that neither TERTpMUT nor ATRX mutations are a negative prognostic factor in IDH-mutant glioblastomas." (PMID 30279357, 2018). "Available glioblastoma samples were also tested for the presence of IDH1 R132H and ATRX mutations." (PMID 29200599, 2017). "Ebrahimi and colleagues found these patients to have H3F3A G34 or K27 mutations, which is concordant with Ikemura and colleagues’ finding of ATRX-loss glioblastomas in younger patients being most commonly non-hemispheric in location." (PMID 29034211, 2017). "Targeting ATRX and its pathways may improve the radiosensitivity of glioblastoma." (PMID 38898533, 2024). "Pathology includes glioblastoma (3/3), methylguanine-DNA methyltransferase (MGMT) methylated (2/3), isocitrate dehydrogenase 1 (IDH1) mutant (0/3), epidermal growth factor receptor (EGFR) amplification (0/3), and α thalassemia/mental retardation syndrome X‐linked (ATRX) (3/3)." (PMID 36148206, 2022).
glioblastoma (continued). "In the specific case of glioblastomas, these authors found proof of biallelic expression in females of KDM6A (encodes the lysine-specific demethylase 6A), KDM5C (encodes the lysine demethylase 5C), DDX3X (encodes a DEAD-box helicase 3 X-linked), and ATRX (encodes the ATRX chromatin remodeler)." (PMID 33752729, 2021). "In combination with loss of nuclear ATRX expression, IDH1, 1p/19q and TERT promoter mutations define the most frequent type of infiltrative astrocytoma, while mutations in the EGFR gene (seen in 35 % of all cases of glioblastoma) are associated with primary glioblastoma." (PMID 26839018, 2016). "ATRX, OLIG2, MGMT, and IDH2 were selected due to their critical roles in glioblastoma biology and prognosis." (PMID 40282990, 2025). "Histopathology confirmed glioblastoma IDH-wildtype CNS WHO grade 4 with immunohistochemistry, showing glial fibrillary acidic protein marker and ATRX positivity but IDH-1 R132H negativity." (PMID 40282523, 2025). "Key molecular players, such as ATRX, OLIG2, MGMT, and IDH2 proteins, contribute to critical oncogenic processes like chromatin remodelling, glioblastoma cell fate and de-differentiation, DNA repair and metabolic reprogramming." (PMID 40282990, 2025). "For instance, ATRX binds to regulatory elements of cell cycle genes including CHEK1, as previously reported in a glioblastoma model." (PMID 38978571, 2024). "The highest mutation frequency of BRAF, ATRX, IDH1, CDKN2A, and EGFR was seen in melanoma (SKCM), thyroid carcinoma (THCA), brain lower-grade glioma (LGG), head and neck squamous cell carcinoma (HNSC), and glioblastoma multiforme (GBM), respectively." (PMID 37000317, 2023). "ATRX and IDH1 mutations appeared to be more commonly altered in glioblastoma that lack RTK genomic variations, genetically resembling to that of secondary GBM." (PMID 32794373, 2020). "Other immunohistochemistry markers usually considered and analyzed for glioblastoma are Glial Fibrillary Axonal Protein (GFAP), S-100, vimentin, oligodendrocyte transcription factor 2 (Olig2) and ATRX, with some finding at least one positive marker in more than 90% of glioblastomas." (PMID 39518074, 2024).
glioblastoma (continued). "Samples with astrocytic morphology, with high-grade histological features (mitotic activity with microvascular proliferation and/necrosis), negative for IDH on IHC, and with retained ATRX protein expression were considered glioblastoma (IDH wt)." (PMID 37358939, 2023). "Furthermore, higher grade, IDH-wild type, non-1p19q codeletion, ATRX-wild type, MGMT unmethylated, TERT mutant, and glioblastoma were correlated with a higher CRGRS." (PMID 36267281, 2022). "The loss of ATRX impaired the non-homologous end joining activity and increased MSI in glioblastoma, rendering higher sensitivity to DNA-damaging agents." (PMID 33678158, 2021). "ATRX variation is a prognosis marker, rarely observed in IDH-wild type glioblastoma." (PMID 34683160, 2021). "We found reads aggregated around CTCF motifs defined via the JASPAR database in ATRX-wildtype cells, likewise in an ATRX-wildtype glioblastoma specimen used as a positive control, but this was not the case in ATRX-KO cells." (PMID 34763709, 2021). "Also molecular markers known to influence glioblastoma prognosis—such as IDH mutation status, MGMT promoter methylation, and ATRX expression—were not assessed, which restricts comprehensive molecular stratification." (PMID 41577996, 2026). "Similarly, ATRX and H3F3A mutant glioblastoma showed hypomethylation of subtelomeric regions." (PMID 41212394, 2025). "Glioblastoma patients lacking ATRX expression appear to benefit more from this treatment." (PMID 38674026, 2024). "If IDH is wildtype (negative), the diagnosis is glioblastoma, where ATRX is usually retained." (PMID 39165459, 2024). "In summary, we have uncovered the existence, in anaplastic astrocytomas but not in glioblastomas with the same IDH and ATRX mutations, of a correlation between patient age and the level of activity of ALT, a telomerase-independent pathway of telomere maintenance." (PMID 31706351, 2019). "We have previously shown that approximately 20% of pTERT wild-type glioblastomas (GBM) activate ALT, most without detectable ATRX loss by IHC, and that these tumors tend to have a better prognosis." (PMID 41422096, 2025). "Histopathological examination confirmed glioblastoma IDH-wildtype CNS WHO grade 4, ATRX positivity, and the absence of 1q/19q co-deletion." (PMID 40282523, 2025). "Approximately 83% of primary glioblastomas were ATRX positive, respectively, and all IDH-1 mutant cases were ATRX negative." (PMID 38003967, 2023). "Out of 25 cases of glioblastoma, IDH was negative, and ATRX was retained in all cases." (PMID 39165459, 2024).